LEP (leptin)
Diseases named in the same sentence as LEP in open-access papers (continued):
Sharing a sentence is not in itself a finding about the gene and the disease.
endometriosis (continued). "Interestingly, in a previous clinical study positive correlation between PF and serum leptin concentrations was found among fertile patients with endometriosis." (PMID 38567305, 2024). "In conclusion, the role of leptin as a reliable biomarker of endometriosis remains controversial." (PMID 38567305, 2024). "In addition, higher expression of levels of leptin and leptin-receptor protein was shown in endometrial tissues of women with endometriosis." (PMID 38075048, 2023). "In addition, the leptin levels were lower in women with advanced-stage disease than in women with early endometriosis." (PMID 38075048, 2023). "Our results suggest that leptin and its receptor are critical for endometriosis development." (PMID 36140261, 2022). "Higher serum leptin levels were observed in women with endometriosis in comparison to the controls." (PMID 36289764, 2022). "Clinically, there are some data that women with endometriosis have mitochondrial dysfunction {Hsu, 2015 #1611}, which may also involve leptin signaling." (PMID 36140261, 2022). "Importantly, we revealed that aberrant high levels of leptin concentration significantly increased endometriosis development compared with vehicle treatment group in control mice with normal body weight." (PMID 36140261, 2022). "If the pathophysiologic mechanisms of endometriotic lesion formation in mouse models could be translated to human biology, disruption of leptin signaling may provide a novel therapeutic target for endometriosis." (PMID 36140261, 2022). "The concentration of leptin in the peritoneal fluid of endometriosis patients was found to be consistently high, while serum leptin concentration may be elevated or comparable." (PMID 36140261, 2022). "The disruption of leptin signaling hinders the induction of endometriosis in mouse models." (PMID 36140261, 2022). "Importantly, our studies revealed a critical role of leptin in the pathogenesis of endometriosis in mouse with normal body weight." (PMID 36140261, 2022). "Additionally, rescuing leptin signaling by treatment with leptin restored the disease activity and even affected the progression of already existing endometriosis at higher doses." (PMID 36140261, 2022). "This weight loss pattern may be related to an increase in the serum and PF leptin levels (an anti‐hunger hormone) observed in endometriosis patients." (PMID 34806344, 2021). "Leptin also seems to be involved on pathogenesis of endometriosis." (PMID 34684349, 2021). "Nevertheless, the large NHS II study did not reveal any significant associations between endometriosis and adiponectin (RR 0.8, 95% CI 0.5–1.2, p 0.48) or leptin-to-adiponectin ratio (RR 0.8, 95% CI 0.4–1.4, p 0.14) after adjustment for BMI." (PMID 33986637, 2021). "This should induce a local impact of leptin on endometriosis." (PMID 34684349, 2021). "Serum leptin can be used as a marker of severity of endometriosis." (PMID 32963544, 2020). "Leptin has recently been suggested to be involved in unexpected functions, specifically the process of angiogenesis and immune response which are one of the most important factors involved in the pathogenesis of endometriosis." (PMID 32963544, 2020). "Leptin also had immune-regulatory, proinflammatory, and neoangiogenesis functions, so it may play a role in pathogenesis of endometriosis." (PMID 32963544, 2020). "The serum leptin level and the result revealed statically significant increase in the endometriotic group which has a similar match with our study which indicates the possible role in the pathogenesis of endometriosis." (PMID 32963544, 2020). "Leptin is now recognized to have immune-regulatory, pro-inflammatory, and neoangiogenesis functions, and it is thought to have a role in the pathogenesis of endometriosis." (PMID 26242176, 2015).
endometriosis (continued). "Although this study does not give a clear picture of the role of leptin in the development and progression of peritoneal implants, it contributes new data that might be useful to elucidating the enigma that is the role of leptin in endometriosis disease." (PMID 26242176, 2015). "Increased serum leptin/BMI ratio was found in endometriosis patients." (PMID 23634146, 2013). "In this study, leptin/BMI ratio in serum and peritoneal fluid and gene expression of leptin and long form leptin receptor (OB-RL) were assessed in eutopic and ectopic endometria of women with endometriosis and controls." (PMID 23634146, 2013). "The increase in leptin and leptin receptor expression in the ectopic endometrium of women with endometriosis may lead to increased leptin signaling in implants, resulting in proliferation, neoangiogenesis, and maintenance of ectopic endometrial tissue." (PMID 23634146, 2013). "However, because some participants had their samples collected in the proliferative phase, we observed that serum and PF leptin/BMI ratios were comparable in the two phases in both endometriosis and control participants." (PMID 23634146, 2013). "The serum leptin/BMI ratio was significantly higher in the endometriosis group than in controls." (PMID 23634146, 2013). "In the context of endometriosis, leptin may contribute to the pathogenesis and progression of endometriotic lesions by influencing local angiogenesis and inflammation, and altered levels may also contribute to the impaired eating habits of many women with this condition." (PMID 41563503, 2026). "Subsequently it has been shown, that leptin exert pleiotropic actions by regulating immune homeostasis, promoting neoangiogenesis and reproduction, so it is thought that this molecule may also play a role in pathogenesis of endometriosis." (PMID 38567305, 2024). "Furthermore, the study assessed the potential role of leptin as a biomarker of endometriosis." (PMID 38567305, 2024). "Hence, further research is imperative to elucidate the role of leptin in endometriosis." (PMID 38567305, 2024). "Experimental studies found that leptin enhances the proliferation of both eutrophic and ectopic endometrial stromal cells in endometriosis, stimulates the migration and invasion of endometrial cells, and was essential for angiogenesis in a mouse model of endometriosis." (PMID 38075048, 2023). "Finally, there is increasing evidence that there may be different clinical or biochemical subtypes of endometriosis; we speculate that leptin signaling may play a role in the pathogenesis of at least some endometriosis subtypes." (PMID 36140261, 2022). "Leptin is a cytokine produced mainly by adipocytes, which not only plays a role in energy balance and homeostasis but also in pro-inflammatory and angiogenetic functions, which may be fundamental in the pathogenesis of endometriosis." (PMID 36140261, 2022). "Leptin may be used with other markers as combination to predict the severity of endometriosis." (PMID 32963544, 2020). "In view of the potential role of leptin in peritoneal endometriosis, we evaluated the leptin levels in the serum and peritoneal fluid and the protein expression in three different peritoneal ectopic implants in patients who underwent surgery for severe endometriosis." (PMID 26242176, 2015). "In fact, recent studies have shown that combining the serum concentration of various proteins that are differentially expressed in women with and without endometriosis, including leptin, would greatly increase diagnostic accuracy as compared to assaying each protein alone." (PMID 23634146, 2013). "Therefore, leptin signaling seems to be a necessary component of lesion proliferation, initial vascular recruitment, and maintenance of neoangiogenesis in a murine model of endometriosis." (PMID 23634146, 2013).
endometriosis (continued). "The higher serum leptin/BMI ratio observed in the endometriosis group as compared to the control group may be due to endometriotic implants rather than adipose tissue, since leptin and OB-RL transcripts were similar in the fat tissue of endometriosis and control participants." (PMID 23634146, 2013). "In a mouse model of endometriosis, HFD-induced obese mice increased lesion number and weight, which depended on leptin or leptin receptor." (PMID 38559689, 2024). "Interestingly, while leptin, primarily produced by adipocytes, might suggest a higher occurrence of endometriosis in women with an increased BMI, there exists an inverse correlation between BMI and the prevalence of endometriosis." (PMID 38567305, 2024). "The levels of angiogenin, CD105, ICAM-1, CXCL10, leptin, lipocalin-2, MMP-9, osteopontin, RBP4, PAI-1, ABP, CD31, TIM-2, and VCAM-1 were higher in the endometriosis group than in the control group." (PMID 34072419, 2021). "This study explores the changes of serum levels of Cancer Antigen 125 (CA125), leptin, resistin, homocysteine, and total antioxidant capacity (TAC) in a rat model of endometriosis and the effect of curcumin treatment on these factors." (PMID 30806992, 2019). "In this study, evaluation of serum level of leptin, resistin, homocysteine, CA125, and TAC was selected to find their possible alteration in an induced autograph model of endometriosis and following treatment with curcumin." (PMID 30806992, 2019). "The results of present study do not support the relevance of leptin concentration determination as a biomarker of the endometriosis." (PMID 38567305, 2024). "Plasma and peritoneal leptin/BMI ratios were significantly lower in women with endometriosis - related primary infertility compared to women with endometriosis without primary infertility (0.640 ± 0.502 vs 0.878 ± 0.623, p < 0.05)." (PMID 38567305, 2024). "The meta-analysis of 25 studies including 2,645 women (1,362 with endometriosis and 1,283 without) showed higher serum leptin levels and leptin/BMI ratio in women with endometriosis." (PMID 38075048, 2023). "A meta-analysis of 25 studies with 2645 participants showed that leptin levels (weighted mean difference (WMD) = 4.45 mg/mL, 95% CI = 2.42–6.49, p < 0.01) and leptin/BMI ratio (WMD = 0.32 mg/mL, 95% CI = 0.23–0.42, p < 0.001) were significantly higher in women with endometriosis." (PMID 36140261, 2022). "In addition to its role in energy homeostasis, leptin signaling contributes to immune and angiogenic processes induced by IL-8, IL-6, TNF, and IL-1β and known to be crucial in the pathogenesis of endometriosis." (PMID 36140261, 2022). "The effects of BMI, WHR, and WHRadjBMI on endometriosis, PCOS, pre-eclampsia, and UF were attenuated (95% CIs of ORs all contain 1) when adjusted for leptin, fasting insulin, or insulin sensitivity as measured by the modified Stumvoll Insulin Sensitivity Index (ISI)." (PMID 35104295, 2022). "The study revealed that the level of leptin was higher in the endometriosis group but had no clear role in the progression of disease." (PMID 32963544, 2020). "The peritoneal and serum leptin levels in UI, however, were not different from that of females of endometriosis, measured in the late follicular phase." (PMID 32025443, 2019). "In contrast, the leptin levels in the PF were not different (control = 6.68 ± 0.43, endometriosis = 7.71 ± 0.59, ng/mL, p = 0.18)." (PMID 26242176, 2015). "In contrast, small studies have shown that PF leptin is significantly higher in endometriosis patients compared to those without the disease and the presence of OE had no significant main effect on leptin concentration." (PMID 24401660, 2014). "Moreover, this same report showed that treatment of endometriotic cells with leptin induced the expression of OBR mRNA, which suggests autocrine and paracrine involvement of the leptin system in endometriosis." (PMID 24401660, 2014).
endometriosis (continued). "Nevertheless, despite the specificities of each study, all seem to indicate (at least with the current commercially available kits) that PF leptin alone is not a good marker to screen for the presence, location, or severity of endometriosis." (PMID 23634146, 2013). "Our study aligns with the thesis, that peritoneal fluid and serum leptin level may not significantly differ between patients with endometriosis and the control group." (PMID 38567305, 2024). "However, the endometrial leptin mRNA expression was similar in women with and without endometriosis." (PMID 38075048, 2023). "Serum leptin levels appear to be similar in women with and without endometriosis at any stage." (PMID 24401660, 2014). "Leptin and OB-RL mRNA expressions were also significantly higher in ectopic endometrium when endometriosis patients were stratified into minimal/mild and moderate/severe endometriosis groups as compared to the eutopic endometrium of non-endometriosis controls." (PMID 23634146, 2013). "Furthermore, leptin has been shown to be essential for angiogenesis in an endometriosis mouse model, and studies reporting leptin to activate VEGF-A expression and the detection of elevated VEGF-A in endometriosis both suggest that the angiogenic effect of leptin is mediated via this growth factor." (PMID 36289764, 2022). "An interesting finding about leptin and endometriosis is that patients with peritoneal implants at all stages of endometriosis show higher PF leptin concentrations than women in whom no implant was observed, suggesting that leptin may play a role in the development of peritoneal endometriosis." (PMID 26242176, 2015). "Although this study does not provide a clear picture of the role of leptin in the development and progression of peritoneal implants, it contributed new data that might be useful to elucidating the enigma that is the role of leptin in endometriosis disease." (PMID 26242176, 2015). "Another limitation, leptin levels and LEPR expression in women with endometriosis and in different genotypes could not be directly determined due to the lack of an adequate sample for measurement." (PMID 40673025, 2025).
prediabetes (40 papers, 2013 to 2026). "Plasma adiponectin, visfatin, leptin, and resistin levels were measured in all the subjects, and the related risk factors of colonic polyps in prediabetes subjects were analysed." (PMID 32393372, 2020). "Results from the random forest analysis indicate that particularly age and waist circumference, but also leptin and 6 single-nucleotide polymorphisms out of 41 are associated with an elevated risk for prediabetes." (PMID 24098730, 2013). "In this study, we investigated whether changes in plasma adiponectin, visfatin, leptin, and resistin levels are associated with the onset of colonic polyps in prediabetes subjects." (PMID 32393372, 2020). "Additionally, epidemiological studies have consistently shown that leptin is associated with glucose metabolism in patients with prediabetes." (PMID 23552170, 2013). "To summarize, engaging in physical activity, particularly aerobic exercise, results in increased adiponectin levels and decreased leptin levels in individuals with prediabetes and diabetes." (PMID 39444577, 2024). "The authors found that physical activity promotion with or without dietary or lifestyle modifications did not affect adiponectin level; however, it did show a positive effect on leptin in individuals with prediabetes." (PMID 38068801, 2023). "In participants with prediabetes serum leptin levels tended to be higher (19.5 μg/L [13.5; 27.7] vs. 16.7 μg/L [12.0; 24.3] in female and 7.8 μL/L [4.6; 9.9] vs. 6.5 μg/L [3.9; 9.7] in male participants)." (PMID 35745267, 2022). "Our meta-analysis showed that ginseng consumption did not affect anthropometric measurements (BW, BMI, and WC) and adipocytokines (adiponectin and leptin) in individuals with prediabetes and T2DM." (PMID 35745129, 2022). "We found that physical activity promotion with or without dietary or lifestyle modification did not affect adiponectin level, however showed a positive effect on leptin in individuals with prediabetes." (PMID 33211181, 2021). "In conclusion, five months of a high-fat high-sucrose diet induced prediabetes in males and female rats, with sex differences in weight gain, leptin level, glucose tolerance and heart/tibia ratio." (PMID 34578791, 2021). "This research explores the relationship between plasma adiponectin, visfatin, leptin, and resistin levels and the development of colonic polyps in prediabetes subjects." (PMID 32393372, 2020). "Until now, the correlation between plasma adiponectin, visfatin, leptin, and resistin levels and the incidence of colonic polyps in the prediabetes population, as well as the number and degree of malignant polyps in the colon, is still unclear." (PMID 32393372, 2020). "From binary logistic regression analysis, HOMA%B, HOMA-IR and leptin were found to be significant determinants of NAFLD only in female prediabetes." (PMID 26569494, 2015). "In addition, hypothyroid patients displayed increased circulatory leptin levels, suggesting its contribution to the development of IR, prediabetes, and DM." (PMID 38667278, 2024). "Interestingly, our group showed that Jordanian patients who have prediabetes, a state characterized by elevated levels of serum leptin, are more likely to carry the GA genotype of rs2167270." (PMID 37241229, 2023). "Another contributing factor that is related to prediabetes could be the higher percentage of body fat, particularly subcutaneous, and the adipose tissue derived leptin hormone in women vs. men." (PMID 33679574, 2021). "In the first comparison, the physical activity intervention administered along with or without dietary or lifestyle modification may reduce the level of leptin and IL-6 in individuals with prediabetes." (PMID 33211181, 2021). "Another study in relatively lean rural Chinese adults found that plasma leptin levels are associated with IR and prediabetes, which were not totally explained by adiposity." (PMID 33076921, 2020).